OXT (oxytocin/neurophysin I prepropeptide)
Diseases named in the same sentence as OXT in open-access papers (continued):
Sharing a sentence is not in itself a finding about the gene and the disease.
autism (continued). "Indeed, recent clinical trials indicate that intranasal administration of OXT may serve as a promising treatment for various neurological disorders, including dementia and autism." (PMID 40143166, 2025). "This indicates that RORA may also play a role in OXT expression that adds to the significant effect of ERβ, which is consistent with previous findings that RORA plays a critical role in embryo development and is associated with autism development." (PMID 35370982, 2022). "We tentatively predict that AGTR2 gene variants and their effects on the OXT-AVP pathways involved in major physiological processes, learning, and social behavior may contribute to further understanding of the link between prematurity and autism." (PMID 30109601, 2019). "Accumulating evidence suggests that the neuropeptide oxytocin (OXT) can enhance empathy although it is unclear which specific behavioral and neural aspects are influenced, and whether the effects are modulated by culture, sex, and trait autism." (PMID 30108475, 2018). "Disorders in OXT secretion and functions can cause a series of aberrant social behaviors, such as depression, autism, and schizophrenia as well as disturbance of nonsocial behaviors/functions, such as anorexia, obesity, lactation failure, osteoporosis, diabetes, and carcinogenesis." (PMID 24967304, 2013). "This study assessed the clinical utility of blood OXT serum levels and the OXT receptor (OXTR) genotype as biomarkers of autism and its severity in a pediatric population in Iraq." (PMID 35316293, 2022). "How do these conceptualizations of loneliness, and autism, relate to theory and evidence for the contextual adaptive significance of AVP and OXT?" (PMID 35586834, 2022). "Given the significance of OXT for autistic deficits, we followed OXT effects on intestinal peristaltism and gastric emptying in our VPA rat model of autism." (PMID 32485966, 2020). "Altered blood levels of OXT have been reported in children with ASD and premature infants, underscoring the importance of OXT-AVP pathways in both prematurity and autism." (PMID 30109601, 2019). "Because of the close relationship between OXT and social behavior, we examined the role of OXT in the VPA-induced rat model of autism." (PMID 30356897, 2018). "Moreover, the results presented here further corroborate the hypothesis that alterations in the OXTergic system are involved in the pathophysiology of autism and that administration of OXT to such altered system might restore a balance in the neural circuitries involved in social behavior." (PMID 25225634, 2014). "Recently published results from clinical trials suggest little to no therapeutic effect of OXT in patients with autism, but others show dose-dependent, and age-dependent effects." (PMID 38102481, 2024). "By contrast, trait-based loneliness is much more closely akin to autism, and should, by the hypothesis and evidence described here, involve alterations to the AVP and/or OXT systems that are maladaptive and present from birth or environmentally induced." (PMID 35586834, 2022). "The lack of an effect of OXT on social behaviors in sham animals in the current study supports previous findings in which OXT did not affect social novelty in wild-type mice and only increased preference for social novelty in mice that exhibit autism-like behaviors." (PMID 34035071, 2021). "Endogenous OXT release could also be stimulated pharmacologically to achieve more physiological-like conditions; for instance, MC4R agonists potentiate central OXT release and rescue social deficits in a mouse model of autism." (PMID 31998152, 2019). "Similarly, rodent models of autism and depression frequently report changes in AVP and OXT systems." (PMID 31404254, 2019).
autism (continued). "However, another study that included 15 reports on a different clinical population (i.e. autism, borderline personality disorder, depression, schizophrenia, and drug dependence), found that OXT did not significantly influence any of the same behavioral outcomes." (PMID 31998152, 2019). "There were no pre-treatment differences between the OXT and PLC group regarding demographics, autism-spectrum quotient (AQ), attachment to stimulus, sex, or neuropsychological performance." (PMID 26449882, 2015).
depression (70 papers, 2010 to 2026). "In a study, polymorphisms in OXT rs2740210 interacted with early-life adversity to predict variation in breastfeeding duration since variants in OXT rs2740210 moderated the effects of early adversity on depression." (PMID 39201521, 2024). "Taken together, our data indicate that ErbB4 in the PVH regulates metabolism likely through regulation of OXT expressing neurons, reveal a novel function of ErbB4 and provide insight into pathophysiological mechanisms of depression-associated obesity." (PMID 37669858, 2023). "In addition, recent studies have implicated the potential roles of OXT in anxiolysis and shown therapeutic benefits of OXT for subsets of patients with depressive disorders." (PMID 30158853, 2018). "Hypermethylation in the promoter region of the OXT gene, found in this study to be associated with child maltreatment, was in the same region and coincided with the direction of the effect in previous studies that examined the association between the intermediate phenotype of empathy and depression." (PMID 34789725, 2021). "Moreover, postmortem analyses indicate an increased number of OXT-expressing neurons in the paraventricular nucleus in depression, which may be associated with the activation of the hypothalamic-pituitary-adrenal axis." (PMID 22510359, 2012). "Stress-related overactive OXT–CRH brain systems can induce major depressive disorder and bipolar disorder." (PMID 40559398, 2025). "A previous study found that serum OXT was significantly negatively correlated with Hamilton Depression Scale score." (PMID 38017588, 2023). "In a socially isolated model of depression, OXT mediated the development of depressive-like behaviors following neuronal injury in mice." (PMID 38017588, 2023). "Human behavioral studies have shown that lower levels of plasma and peripheral OXT are found in patients with depression, SZ, and ASD." (PMID 36429060, 2022). "In clinical HD, a positive correlation between OXT plasma levels and depression in both motor manifest and premanifest HD patients has been observed." (PMID 36187357, 2022). "Second, patients with higher OXT plasma levels show fewer symptoms of major depression, post-partum depression, and anxiety symptoms." (PMID 34471100, 2021). "Patients with depression, symptoms of depression and separation anxiety during pregnancy have been shown to have lower plasma OXT concentrations." (PMID 32438751, 2020). "In patients with depression, the concentration of OXT has been shown to be lower compared to control subjects." (PMID 32438751, 2020). "Future studies should include detailed measures of hyper- or hypomentalizing ratings for confounding symptoms like depression and physiological measures of the stress response together with OXT levels should be taken." (PMID 32255800, 2020). "Plasma OXT levels have a positive correlation with quality of life in major depressive disorder (MDD) and predict the outcome of psychotherapy in chronic depression." (PMID 32733584, 2020). "Different studies have shown that intranasal administration of OXT ameliorates depression-like behavior in rats and in human social behaviors." (PMID 32438751, 2020). "Studies conducted in individuals suffering from depression or emotional distress suggest not only gender-specific reductions of baseline OXT, but also a dysregulated or more variable pulsatile OXT release." (PMID 30481342, 2019). "As an example, subjects with major depression showed increased number of OXT-immunoreactive neurons in the PVN of the hypothalamus." (PMID 31998152, 2019). "This network consisted of a number of molecules previously reported to be associated with depression (according to a PubMed search), such as CYP3A5, VAMP2, CSGALNACT1, CASP8, CRHR2, PKD2, and OXT." (PMID 26728011, 2016).
depression (continued). "Similarly, behavioral despair (a behavior associated with depression) was shown to enhance OXT synthesis and secretion in the paraventricular nucleus, supra-optic nucleus, frontal cortex, amygdala, and hippocampus, as well as OXT release from the posterior pituitary into the blood." (PMID 26858594, 2015). "In depression, serum OXT levels have been found to be reduced, which included patients with bipolar depression." (PMID 22510359, 2012). "Taken together, the present evidence from the few studies assessing OXT in animal models of depression is inconclusive regarding a potential antidepressant-like effect of OXT." (PMID 27713275, 2010). "In rats exposure to forced swimming stimulates the release of OXT within the central amygdala (CeA) again suggesting a link between OXT and depression." (PMID 27713275, 2010). "Also, MS-induced depression-like behaviors were attenuated by OXT mediated improvement of mitochondrial function and immune-inflammatory response in the hippocampus." (PMID 38017588, 2023). "Furthermore, the results of the present research demonstrated that OXT significantly leads to the improvement of depression." (PMID 35065634, 2022). "Preclinical findings suggest that long-term isolation down-regulates OXTR mRNA transcription and contributes to the development of depression in isolated mice – which might be attenuated through intracentral amygdala injection of OXT." (PMID 35672748, 2022). "Furthermore, the effects of intranasal administration of OXT on stress-related disorders, such as anxiety, depression, and posttraumatic stress disorders, have been reported in various clinical studies." (PMID 32733584, 2020). "Lower plasma OXT levels have been reported in patients with major depression." (PMID 27536785, 2016). "In a similar vein, women at risk of developing postpartum depression had lower OXT plasma concentrations than women who had no increased risk for postpartum depression, and OXT serum levels in mid-gestation predicted postpartum depression symptoms." (PMID 22510359, 2012). "Moreover, assessment of the role of OXT in additional endophenotypes of depression is sorely warranted, for examine cognitive dysfunction and sleep disturbances under control and stess-altered conditions." (PMID 27713275, 2010). "Current drug discovery status of OXT and endophenotypes of depression." (PMID 27713275, 2010). "However, abnormal values of OXT levels in depression require further investigation." (PMID 22997507, 2012). "OXT and OXTR genes are important regulators of nursing behavior in mothers, which has a connection with the depression-like behaviors of the postpartum period." (PMID 39201521, 2024). "Maternal separation disorder involves the expression of OXT+ neurons, OXTR binding, and plasma OXT levels in key brain regions related to depression." (PMID 37445607, 2023). "Studies found that OXT methylation levels in MDD inpatients were significantly lower than in healthy controls, suggesting that changes in the epigenetic characteristics of the OXT system may constitute a vulnerability factor for susceptibility to depression (Sanwald and Widenhorn-Müller, 2020)." (PMID 38249586, 2023). "Different studies have found a correlation between OXT concentrations in blood and some stress-related disorders such as post-traumatic stress disorder (PTSD), anxiety disorders and depression." (PMID 32438751, 2020). "In our study, peripheral OXT administration in HFD-fed mice restored social cognitive function, object cognitive function, object location memory, and depression-like behavior." (PMID 32719656, 2020). "Lower levels of peripheral OXT have also been identified in some studies of autism spectrum disorders (ASD), depression and schizophrenia, although the findings vary." (PMID 27536785, 2016).
depression (continued). "The patients were then treated with electroconvulsive therapy (ECT), venlafaxine, an SSRI, or a tricyclic antidepressant and after a positive response as measured by the Hamilton Depression Rating Scale (HDRS), plasma OXT levels were re-assessed." (PMID 27713275, 2010). "Mothers who experienced early adversity displayed increased depression and reduced breastfeeding only if they carried the CC genotype of OXT rs2740210 but not if they possessed the AA/AC genotypes." (PMID 39201521, 2024). "We hypothesize that comparing salivary OXT, alpha-MSH, beta-endorphin, neurotensin, and substance P in patients with depression and controls could be as effective as comparing their serum levels." (PMID 39347144, 2024). "Despite so much preclinical and clinical evidences for the intervention effects of OXT in depression, its biological mechanisms have not been systematically elucidated." (PMID 38017588, 2023). "In humans, OXT levels have been observed to be significantly lower in both psychotic and nonpsychotic depression, as well as bipolar depression." (PMID 30719038, 2019). "The expression of oxytocin (OXT) in hypothalamic paraventricular nucleus (PVN) of patients with depression was increased significantly, and androgen could directly inhibit the expression of the OXT gene by combining ARE with the human OXT gene promoter, leading to a potential neuroprotective effect." (PMID 35663561, 2022). "The objective of this study was to determine whether serum levels of OXT in adolescent patients with treatment-resistant depression differ from those of sex- and age-matched individuals with non-treatment-resistant depression or controls." (PMID 27536785, 2016).
Obesity (42 papers, 2011 to 2025). Accumulation of substantial excess body fat. "The hyperphagia is also partially mediated by impaired Trpc5 actions on OXT neurons in the PVH as deletion from this site caused hyperphagic obesity, which was reversed by OXT supplementation." (PMID 38959890, 2024). "We measured OXT levels in youth with severe obesity undergoing SG or standard therapy and examined associations with weight, body composition, and bone parameters." (PMID 37373292, 2023). "In line with the specificity of our results for males, only male mice with OXT deficiency due to ablated OXT neurons were more likely to develop obesity when put on a high-fat diet." (PMID 36042529, 2022). "Conversely, reduced OXT signaling is associated with obesity and reduced energy expenditure and thermogenesis in brown adipose tissue (BAT)." (PMID 36232550, 2022). "In contrast, reduced OXT signaling is associated with obesity and reduced energy expenditure and thermogenesis in BAT." (PMID 34646154, 2021). "The current study examined the effects of chronic OXT infusions on adipose tissue inflammation in a murine model of obesity and diabetes, the leptin receptor-deficient (db/db) mouse." (PMID 32819381, 2020). "Recent studies have shown that the impairment of OXT signaling is associated with disturbance of metabolic homeostasis, resulting in obesity and diabetes." (PMID 29867762, 2018). "In general, the magnitude of weight loss induced by OXT treatment was more appreciable in patients with higher degree of obesity." (PMID 23700406, 2013). "Furthermore, due to their role in regulating dietary preference, impaired signalling through FGF21 and OXT underlies dietary choices that exacerbate obesity and linked diseases." (PMID 40225784, 2025). "Under physiological conditions, leptin activates OXT-producing neurons in the paraventricular nucleus; prenatal nutrient deprivation can disrupt this interaction, promoting leptin resistance and increasing long-term risk of obesity." (PMID 41614746, 2025). "Mutations in OXT or its receptor (OXTR) are directly associated with obesity in animals and humans." (PMID 34646154, 2021). "Given that systemic inflammation has been associated with the pathophysiology of obesity and T2D, the anti-inflammatory actions of OXT/OXTR may also be important in attenuating disease progression." (PMID 32819381, 2020). "For example, OXTR and OXT deficient mice exhibit late onset obesity and insulin resistance." (PMID 32819381, 2020). "Conversely, the anti-inflammatory actions of OXT described in the current study may have utility as a therapeutic treatment to ameliorate some of the deleterious consequences associated with obesity." (PMID 32819381, 2020). "Both OXT- and OXT receptor-deficient mice developed late-onset obesity." (PMID 29867762, 2018). "Supplementation of OXT in male and female OXT-Trpc5-KO mice reduced food intake and body weight to levels comparable to WT mice, suggesting that OXT analogs/receptor agonists could be effective in treating human obesity due to TRPC5 deficiency." (PMID 38959890, 2024). "Animal models with OXT or OXTR knockout consistently show late-onset obesity, reduced thermogenesis, and lower energy expenditure, highlighting OXT’s role in metabolic homeostasis." (PMID 41614746, 2025). "OXT- and OXTR-knockout models reproduce hallmark features seen in humans, including obesity, anxiety-like behavior, social avoidance, and impaired maternal care." (PMID 41614746, 2025). "Data from our cohort demonstrate reductions in serum OXT levels following SG in youth with severe obesity." (PMID 37373292, 2023). "A recent study demonstrated that a single dose of intranasal OXT leads to decreased caloric intake at a subsequent meal in men who are lean, overweight, and with obesity." (PMID 37780616, 2023).